INS (insulin)
Diseases named in the same sentence as INS in open-access papers (continued):
Sharing a sentence is not in itself a finding about the gene and the disease.
Insulin resistance (continued). "A pregnant woman may develop raised blood glucose concentration (hyperglycemia) or GDM if her pancreatic beta-cells are unable to increase insulin secretion and overcome insulin resistance." (PMID 34869515, 2021). "Notably, ND6 methylation was inversely correlated with ND6 mRNA level while positively correlated with BMI, fasting glucose, fasting insulin, and homeostasis model assessment‐insulin resistance (HOMA‐IR) index." (PMID 34141522, 2021). "In addition, it increases insulin resistance by acting on insulin signaling through IRS-1 phosphorylation, thus impairing effective translocation of glucose transporter 4 (GLUT4) and insulin-stimulated glucose uptake." (PMID 33919641, 2021). "Adult female rats were acutely treated with either risperidone (0.1, 0.5, 1, 2, 6 mg/kg), paliperidone (0.1, 0.5, 1, 2, 6 mg/kg) or vehicle and subjected to the glucose tolerance test; plasma was collected to measure insulin levels to measure insulin resistance with HOMA-IR." (PMID 33508013, 2021). "In addition, polymorphisms in CLU have been linked to insulin resistance [by the homeostasis model of insulin resistance [HOMA-IR] and impaired insulin secretion [HOMA-β]]." (PMID 33717095, 2021). "We could not detect an improvement of insulin sensitivity by a conventional insulin tolerance test, most likely due to a severe insulin resistance in Avy and Avy hIAPP, as shown by the severe hyperinsulinemia observed in these mice at 20 weeks of age." (PMID 34088954, 2021). "Additionally, the combined use of high-fat diet with nicotinamide and STZ in ICR mice induced significant insulin resistance, hyperlipidemia, impaired insulin secretion, glucose intolerance, and obesity." (PMID 33435282, 2021). "NNP-2 could improve insulin resistance by modulating the IRS1/PI3K/Akt pathway in insulin-resistant HepG2 cells." (PMID 34071638, 2021). "After 10 days, these mice had similar body weights to the control mice, however, the glucose levels and fasting levels of insulin after intraperitoneal glucose infusion were significantly reduced (~50%), suggesting that irisin can attenuate systemic insulin resistance." (PMID 35392577, 2021). "These cytokines activate the insulin signaling pathway and local and systemic insulin resistance." (PMID 34017260, 2021). "Insulin resistance and hyperinsulinemia are common in individuals with diabesity, C-peptide levels as indicators of insulin secretion have been tested in many studies to see whether hyperinsulinemia is related to cancer risk and mortality." (PMID 33920079, 2021). "In addition, fasting blood glucose (FBG), post-prandial blood glucose (PPBG), fasting insulin (F-Ins) and homeostasis model assessment index for insulin resistance (HOMA-IR) levels were diminished in BSTN1 treated obese rats in contrast to HFD controls." (PMID 34366856, 2021). "Plasma glucose,serum insulin,assessment-estimated insulin resistance,assessment-estimated beta-cellfunction and HbA1c,insulin sensitivity,serum C-reactiveprotein,plasma malondialdehyde,total iron-bindingcapacity, andplasma totalantioxidant capacity were determined." (PMID 34680457, 2021). "In addition, insulin and insulin resistance were improved in a few other TRE studies of overweight or obese subjects." (PMID 33466692, 2021). "Our data obtained in patients with CAD are in agreement with quoted studies, as fasting insulin could be also considered as an indirect measure of insulin resistance." (PMID 34439815, 2021). "In line with our previous report showing a protective effect of Mir181b mimics on insulin resistance, KO mice developed insulin resistance (IR) as shown by improved insulin sensitivity (increased AUC for ITT by 121%) and glucose tolerance (increased AUC GTT by 122%)." (PMID 33416495, 2021).
Insulin resistance (continued). "A second pathway through which a LCD may help to address pathological insulin resistance is through reducing the body's exposure to insulin; thus this dietary approach can help to address this key issue through multiple means." (PMID 34336909, 2021). "Additionally, excessive fatty acids disrupt the insulin signaling pathway, leading to insulin resistance." (PMID 34501978, 2021). "The results presented in this study showed that TG and WC are the main metabolic syndrome factors associated with insulin resistance, basal β-cell function, insulin and HbA1c in non-diabetic FDR men of Type 2 DM." (PMID 34134670, 2021). "In addition, the increase in serum insulin levels in the model group reflects a certain degree of insulin resistance in golden hamsters, making the model more similar to type 2 diabetes." (PMID 35971382, 2021). "The impairment of the kinome response to insulin leads to insulin resistance." (PMID 34445786, 2021). "Moreover, FA metabolites, DAGs and CERs suppressed PI3K/AKT insulin signaling to induce insulin resistance and triggered PKC to generate mitochondrial ROS, which caused CM apoptosis and myocardial necrosis." (PMID 34094645, 2021). "Because insulin and insulin-like growth factors regulate many biological processes such as axonal growth, protein synthesis, and gene expression, insulin resistance and the resultant oxidative stress adversely affect all of these processes, which often occur before onset of overt T2D." (PMID 33679574, 2021). "T2DM, characterized by insulin resistance in target tissue, relatively insufficient insulin secretion, and subsequent β-cell dysfunction, is often non-symptomatic; and patients with T2DM seek medical care only for complications such as vision loss, heart attack, or limb gangrenes." (PMID 34764939, 2021). "Previous research has reported that D-gal regulated the ex pression of Lepr and Egr1 genes, which could reduce insulin sensitivity, and produce insulin resistance." (PMID 33952720, 2021). "However, only 4 studies participants were assessed for insulin, and three studies included insulin resistance (HOMR), which cannot do meta-analysis." (PMID 34543302, 2021). "Therefore, hyperinsulinemia inhibits fibrinolysis in individuals with insulin resistance, and intravenous insulin infusion stimulated PAI-1 secretion in humans." (PMID 34440804, 2021). "As galanin is an important hormone for elevating insulin sensitivity via GLUT-4 translocation, perhaps galanin deficiency may at least be one of the efficient factors responsible for insulin resistance in PCOS." (PMID 33740336, 2021). "These pathways are important contributors in the progression and development of insulin resistance and type 2 diabetes (T2D) via activation of inflammatory cascade, impairment in insulin signaling, and disturbance in systemic glucose homeostasis and lipid profile." (PMID 34155273, 2021). "Second, adiponectin secreted by adipose tissue is negatively related to visceral fat accumulation and insulin resistance and thus could improve insulin sensitivity." (PMID 34202423, 2021). "The cerebrovascular event itself may temporarily reduce insulin sensitivity, and then the insulin resistance prevalence may be overestimated." (PMID 34394128, 2021). "Moreover, Jung-Ting Lee proposed that MMP12 expression significantly promotes insulin resistance and that insulin were regulated by resident macrophages." (PMID 34863141, 2021). "CER produced de novo (especially C16 and C18 CER species) have been well described as playing a crucial role in the development of tissue insulin resistance through targeting several components of the insulin signaling pathway, including insulin receptor substrates (IRS) and Akt." (PMID 34940565, 2021).
Insulin resistance (continued). "HOMA2 provides a measure of insulin resistance derived from fasting blood glucose and insulin levels, as well as measures of β-cell function and insulin sensitivity, which employs a non-linear model and constitutes the updated and recommended version of the original HOMA model." (PMID 33597002, 2021). "Hepatocytes and pancreatic beta cells could be infected by SARS‐CoV‐2 through glycosylated ACE2 receptor, promoting the development of insulin resistance and impaired insulin secretion, inducing hyperglycaemia." (PMID 34277995, 2021). "Specifically, the overexpression of GFAT in tissues involved in glucose uptake through insulin stimulation (adipose tissue and muscle) and that use the GLUT4 promoter produced insulin resistance associated with a decrease in the translocation of the glucose transporter induced by insulin." (PMID 34869586, 2021). "In this study, thiamine decreased the levels of FBG and sera insulin along with reduction of insulin resistance by elevation of insulin function and sensitivity following the decrement of levels of IL-1β, FFA, glycation products, oxidative stress markers, and hepatic expression of NF-kβ." (PMID 33995940, 2021). "Downregulation of miR-190b by directly targeting IGF-1 and ADAMTS9 could regulate lipid metabolism and insulin signaling pathway in vitro and could reduce the hepatic steatosis and insulin resistance in vivo." (PMID 33768092, 2021). "We provide evidence that FNDC4 acts as an endocrine factor, which controls systemic glucose tolerance and responds to insulin-sensitizing treatments such as diet, exercise, or BS in conjunction with the reversal of T2D and improvements in insulin resistance in mice and humans." (PMID 34016966, 2021). "Aspalathin has been shown to ameliorate insulin resistance by enhancing insulin signaling via protein kinase B (AKT) and 5′-Adenosine monophosphate-activated protein kinase (AMPK) activation and by reducing inflammation via protein kinase C (PKC) and nuclear factor-κB (NFκB) pathways." (PMID 35008779, 2021). "Furthermore, increased insulin concentration in serum, implying enhanced insulin resistance, is one of the major markers that distinguish metabolic disorders, such as DM and obesity." (PMID 33800583, 2021). "Although previous reports have mainly focused on the relationship between insulin resistance/insulin sensitivity and adiponectin, the results are somewhat in accordance with these findings, suggesting a protective role of adiponectin against insulin resistance and MetS." (PMID 34779349, 2021). "More specifically, the secretion of TNF-α from the synovial or extra-articular infiltrates might be an important mediator of insulin resistance, as it hampers downstream insulin signaling and by inhibiting adiponectin release." (PMID 34579044, 2021). "This could further contribute to central insulin resistance and poor insulin levels in the brain and CSF, mirroring T1D." (PMID 34725612, 2021). "This may suggest that iIFG and iIGT, albeit they are insulin-resistant states, differ in their pathophysiology and site of insulin resistance." (PMID 33164108, 2021). "Given equivalent intra-patient variability and significantly greater insulin resistance, females can receive the same benefit from safe, effective GC as males, but may require higher insulin doses to achieve the same glycaemia." (PMID 33475909, 2021). "Also, there are some clinically useful replacement measures such as homeostasis model assessment for insulin resistance (HOMA‐IR), quantitative insulin‐sensitivity check index (QUICKI) for assessment of insulin resistance." (PMID 34136166, 2021). "Indeed, it supports insulin resistance by reducing insulin-dependent signal transduction, leading to a decrease in glucose transport and hyperglycemia." (PMID 33920886, 2021). "EVs also impede insulin signaling and precipitate insulin resistance in adipose tissue." (PMID 34861815, 2021).
Insulin resistance (continued). "To address how PPARγ agonism can improve cognition in the absence of insulin resistance, we and others have described neuronal signaling pathways modulated by PPARγ agonism that are not directly associated with glucose uptake and insulin sensitivity." (PMID 33382528, 2021). "Impaired insulin signalling and insulin resistance play a vital role in pathological changes in AD." (PMID 34523794, 2021). "The impairment of insulin sensitivity otherwise referred to as insulin resistance is simply a pathological state where tissues either partly or completely fail to respond to insulin in free circulation which results in elevated fasting insulin and blood sugar levels." (PMID 33953863, 2021). "Insulin resistance (IR) is a condition of impaired tissue response to insulin." (PMID 34557264, 2021). "However, Ex-4 suppressed PA-induced insulin resistance by enhancing the insulin signaling related to insulin response." (PMID 33435277, 2021). "MetS patients with insulin resistance have high circulating insulin levels." (PMID 33842335, 2021). "Khalili proved that they could not only reduce energy intake significantly but also improve insulin resistance through the intragastric administration of lactic acid bacteria in insulin-resistant mice." (PMID 35052765, 2021). "Negative genetic correlations were documented between anorexic patients and metabolic traits such as type 2 diabetes, insulin resistance, blood plasma insulin, leptin, and a significant positive genetic correlation was found with high-density lipoprotein (HDL) cholesterol." (PMID 33953692, 2021). "Consequently, the HFD-TRF group showed significantly lower HOMA-IR, an index of insulin sensitivity, compared with the HFD group, suggesting that TRF attenuates insulin resistance associated with a high-fat diet." (PMID 34836036, 2021). "Furthermore, higher HOMA-IR index and higher serum insulin level post glucose injected in FET-chow group suggested the insulin resistance status." (PMID 33634140, 2021). "However, FBS, insulin, homeostatic model assessment for insulin resistance (HOMA-IR), quantitative insulin sensitivity check index (QUICKI), weight, BMI, hip circumference, and waist-to-hip ratio did not change significantly." (PMID 33552217, 2021). "On the other hand, the addition of insulin sensitizing agents to suppress insulin resistance and excess androgen may ameliorate the results of ovulation induction in PCOS patients." (PMID 33737663, 2021). "Compared to healthy individuals, serum levels of both leptin and GAL were higher in obese children and the levels of GAL were positively correlated with the levels of fasting insulin, homeostasis model assessment-insulin resistance, triglycerides, and fasting glucose." (PMID 33802616, 2021). "Moreover, the vasodilative effect of insulin is abolished in case of insulin resistance, and hyperinsulinemia increases renal sodium reabsorption, thereby promoting hypertension." (PMID 34740359, 2021). "The daily administration of 250 mg of elemental Mg2+ for three months improves glycemic control in T2D subjects as demonstrated by the significant reduction of glycated hemoglobin, insulin levels, C-peptide, and Homeostatic Model Assessment for Insulin Resistance (HOMA-IR)." (PMID 33499378, 2021). "- ↓ plasma triglycerides, liver lipids, liver triglycerides, insulin resistance, fasting glucose, fasting insulin, thoracic circumference, abdominal circumference, products of lipid oxidation, pro-inflammatory cytokine expression (IL-1β);- ↑ anti-inflammatory cytokine expression (IL-10)." (PMID 33693024, 2021). "This suggested that if East Asians had significantly elevated insulin resistance, as much as the Caucasians, their insulin secretion may compensatively increase in NGT study subjects." (PMID 34917033, 2021).
Insulin resistance (continued). "However, in insulin resistance, insulin-stimulated adipocytes, muscle cells, hepatocytes, and other cells fail to appropriately respond to insulin, as the blood glucose levels are constantly high." (PMID 34641407, 2021). "Additionally, high-fat feeding resulted in elevated fasting blood glucose and insulin levels, along with higher homeostasis model assessment insulin resistance (HOMA-IR) compared to lean animals." (PMID 34552556, 2021). "Also, glucose homeostatic parameters including fasting blood glucose (FBG), oral glucose tolerance test (OGTT), glucose transporter 4 (GLUT 4), insulin and homeostatic model assessment of insulin resistance (HOMA-IR) were determined." (PMID 34844584, 2021). "Insulin is a paramount anabolic hormone that promotes energy-storage in adipose tissue, skeletal muscle and liver, and these responses are significantly attenuated in insulin resistance leading to type 2 diabetes." (PMID 34336862, 2021). "The classical phenotype of an obese middle-aged person with insulin resistance, hypertension, dyslipidemia and increased waist circumference does not include all patients with type 2 diabetes, some of whom are older, leaner, or more insulin sensitive." (PMID 34912295, 2021). "In the present study we sought to outline the beneficial effect of menaquinone on insulin resistance development in order to better understand the interplay between vitamin K2 supplementation and accumulation of sphingolipids that interfere with the insulin signaling pathway." (PMID 34204938, 2021). "Spearman's correlation analysis showed that these amino acid levels were positively correlated with metabolic characterization, including food intake, FBG, glucose tolerance, insulin resistance, and serum leptin and insulin levels, among which glycine had the strongest correlation." (PMID 33637880, 2021). "Therefore, insulin resistance and lower insulin secretion are the two coexisting pathophysiological markers in most patients with T2D." (PMID 34497585, 2021). "Moreover, under pathologic cases, such as insulin resistance in T2D, β-cell proliferation is enhanced in response to increased insulin demand." (PMID 33572166, 2021). "In addition, it has been demonstrated that acute exercise ameliorates insulin signaling also in the presence of insulin resistance." (PMID 32737757, 2021). "TNF-α is a mediator of insulin resistance through blocking the action of insulin." (PMID 34712684, 2021). "Higher Δ C-peptide may represent higher endogenous insulin secretion and may be a compensatory factor of insulin resistance due to higher baPWV, which implies that higher Δ C-peptide plays an important role in the progress of arterial stiffness." (PMID 34976408, 2021). "H-Exo PC-induced AhR signaling activation contributes to the development of insulin resistance, but constitutive expression of AhR in AhR transgenic mice has been shown to improve insulin sensitivity, despite exacerbating hepatic steatosis by induction of FGF2151." (PMID 33431899, 2021). "Given evidence that hypothalamic neuroinflammation occurs within one day of HFD exposure, prior to inflammation in peripheral tissues, and central insulin signaling is required for peripheral insulin action, fat-induced hypothalamic insulin resistance merits attention." (PMID 34831343, 2021). "Impaired insulin signaling is the direct reason for insulin resistance." (PMID 34948750, 2021). "Insulin and insulin resistance in males were also higher than in females (p < 0.001)." (PMID 34765049, 2021). "To evaluate the effects on insulin resistance, we measured the fasting insulin level and HOMA-IR." (PMID 34135978, 2021). "In addition, insulin sensitivity in neurons is improved by Ex-4 treatment under PA-induced insulin resistance." (PMID 33435277, 2021).